SPTAN1 (spectrin alpha, non-erythrocytic 1)
Description:
Fodrin, which seems to be involved in secretion, interacts with calmodulin in a calcium-dependent manner and is thus candidate for the calcium-dependent movement of the cytoskeleton at the membrane.
Synonyms: NEAS; SPTA2; DEE5; DEVEP; EIEE5; HMN11; HMND11; SPG91
Tractability: Small molecule: it has a binding pocket of medium quality. Antibody: its Gene Ontology location is reachable by antibodies, with high confidence. PROTAC: ubiquitination databases record sites on it; its protein half-life has been measured.
Gene: Protein-coding gene on chromosome 9 (128,552,558 to 128,633,663, forward strand). Ensembl gene ENSG00000197694.
Subcellular location: Cytoplasm, cytoskeleton; Cytoplasm, cell cortex
Subcellular location (Human Protein Atlas): Microtubules; Vesicles
Pathways (Reactome):
Signal Transduction: RAF/MAP kinase cascade; RHOU GTPase cycle; RHOV GTPase cycle
Developmental Biology: Interaction between L1 and Ankyrins; NCAM signaling for neurite out-growth
Sensory Perception: Sensory processing of sound by inner hair cells of the cochlea; Sensory processing of sound by outer hair cells of the cochlea
Cell-Cell communication: Nephrin family interactions
Immune System: Neutrophil degranulation
Programmed Cell Death: Caspase-mediated cleavage of cytoskeletal proteins
Vesicle-mediated transport: COPI-mediated anterograde transport
Gene Ontology:
Molecular function: cadherin binding; protein binding; actin binding; actin filament binding; structural constituent of cytoskeleton; calcium ion binding; spectrin binding
Biological process: actin cytoskeleton organization
Cellular component: extracellular exosome; extracellular vesicle; cell junction; cortical actin cytoskeleton; cytosol; extracellular region; membrane; plasma membrane; specific granule lumen; spectrin; tertiary granule lumen; cell cortex; cortical cytoskeleton; cuticular plate; cytoskeleton; fascia adherens; lateral plasma membrane; paranodal junction; paranode region of axon; Z disc
Genetic constraint (gnomAD): Loss-of-function variants: 61 observed, 339.92 expected, observed/expected ratio (o/e) 0.18, 90% interval 0.14 to 0.22. The upper end of that interval is the gene's LOEUF score, 0.22, which puts it in group 1 of 6, group 1 being the genes least tolerant of losing a copy. Missense variants: 2,037 observed, 3,284.1 expected, observed/expected ratio (o/e) 0.62, 90% interval 0.6 to 0.64. Synonymous variants: 1,153 observed, 1,230.8 expected, observed/expected ratio (o/e) 0.94, 90% interval 0.89 to 0.98.
Gene-disease validity (ClinGen):
ClinGen rates the evidence that SPTAN1 causes each of these diseases.
genetic developmental and epileptic encephalopathy (autosomal dominant): Definitive. A complex neurodevelopmental disorder characterized by a range of developmental delays and epileptic encephalopathy phenotypes.
Homologues: Orthologues: chimpanzee SPTAN1 (99% identical), macaque SPTAN1 (99% identical), rat Sptan1 (99% identical), dog SPTAN1 (99% identical), mouse Sptan1 (98% identical), rabbit SPTAN1 (98% identical), guinea pig SPTAN1 (95% identical), pig SPTAN1 (94% identical), tropical clawed frog sptan1 (93% identical), zebrafish sptan1 (90% identical), Drosophila melanogaster alpha-Spec (64% identical). Paralogues in human: SPTA1 (55% identical), SPTBN5 (25% identical), SPTBN1 (18% identical), SPTBN2 (17% identical), SPTB (16% identical), SPTBN4 (15% identical), MACF1 (14% identical), DST (14% identical), SYNE1 (12% identical), SYNE2 (10% identical), DMD (9% identical), UTRN (9% identical), and 24 more.
Diseases named in the same sentence as SPTAN1 in open-access papers:
SPTAN1 is named in the same sentence as 77 diseases in open-access papers, as found by Europe PMC text mining. Sharing a sentence is not in itself a finding about the gene and the disease. The quoted sentences say what the papers report.
epilepsy (15 papers, 2012 to 2025). A brain disorder characterized by episodes of abnormally increased neuronal discharge resulting in transient episodes of sensory or motor neurological dysfunction, or psychic dysfunction. "The OTUD7A protein–protein interaction network included synaptic, axonal, and cytoskeletal proteins and was enriched for ASD and epilepsy risk genes (Ank3, Ank2, SPTAN1, SPTBN1)." (PMID 36604605, 2023). "In West Syndrome, associated with SPTAN1 mutations, the patients have epilepsy, profound developmental delay and in addition have shortening of the corpus callosum and cerebellar vermis atrophy." (PMID 23236289, 2012). "Sptan1 mutation is associated with epilepsy, and Sptbn1 is implicated in ASDs." (PMID 33192291, 2020). "Epilepsy has been associated with mutations in the human gene orthologs of cac (CACNA1A/B/E), alpha-Spec (SPTAN1) and slo (KCNMA1)." (PMID 37759179, 2023). "In these disorders and epilepsies, carriers of whole-gene deletions are less severely affected than carriers of single point mutations (e. g., in SCN2A, KCNT1, KCNA2, SPTAN1)." (PMID 38835873, 2022). "Heterozygous or de novo variants in SPTAN1 have been previously implicated in several syndromes with either developmental delay with or without epilepsy, spastic paraplegia or distal hereditary motor neuronopathy." (PMID 41191133, 2025). "Nonerythrocytic αII-spectrin (SPTAN1) variants have been previously associated with intellectual disability and epilepsy." (PMID 36331550, 2023). "Patients with SPTAN1 mutations present severe intellectual disability, no visual tracking, epilepsy and spastic tetraplegia." (PMID 28542170, 2017). "In addition, seizures are described in SPTAN1 mutations and another β-III spectrin knockout and it will be important to search for spectrin mutations in epilepsy patients." (PMID 23236289, 2012). "The SPTAN1 gene is responsible for a broad spectrum of neurodevelopmental phenotypes characterized by moderate intellectual disability, with or without epilepsy and behavioral disorders." (PMID 36393831, 2022). "Eighty-one epilepsy-related genes were detected; the gene most frequently detected was KCNQ2 (nine times), followed by PRRT2 (seven times), SCN1A (six times), SCN2A (five times), SPTAN1 (four times), and TSC2 (four times)." (PMID 35571021, 2022).
colorectal cancer (7 papers, 2014 to 2024). A primary or metastatic malignant neoplasm that affects the colon or rectum. "However, in the case of SPTAN1, evidence has suggested that it could act as a tumor suppressor in some types of cancer, such as prostate cancer, lung cancer, and colorectal cancer." (PMID 35563422, 2022). "By comparing SPTAN1 expression level in DNA mismatch repair- (MMR-) deficient and MMR-proficient colorectal cancer or other cell lines, our group could demonstrate that loss of the MMR protein MLH1 was correlated with a significant reduction of SPTAN1 expression." (PMID 31186638, 2019). "We compared the SPTAN1 expression level of these cell lines with their corresponding MLH1 deficient cell lines, HEK293T or the stably pcDNA3.1+ mock control transfected HCT116 mlh0-1 cell line, respectively and with the MLH1 deficient colorectal cancer cell line RKO using Western blot analysis." (PMID 24456667, 2014).
Intellectual disability (7 papers, 2017 to 2023). "Human mutations in SPTAN1 associated with West Syndrome are characterised by intellectual disability, agenesis of the corpus callosum, and hypomyelination." (PMID 36551785, 2022). "Sptan1 plays a critical role in neurodevelopment and mutations of Sptan1 leads to encephalopathy, intellectual disability and ASD." (PMID 30814930, 2019). "The abnormal expression of Sptan1 may cause early infantile epileptic encephalopathy, intellectual disability, speech impediment and autism." (PMID 37284462, 2023). "For instance, SPTAN1 gene deletion in chromosome 9:(130900001–133,080,000) has been reported to be associated with early infantile epileptic encephalopathy, infantile spasms, intellectual disability, and hypomyelination, and molecular defects of TOR1A gene lead to early-onset primary dystonia." (PMID 30038665, 2018). "Sptan1 is also an important cytoskeletal protein that participates in the construction of the axon initial segment and the abnormal expression of Sptan1 may lead to early infantile epileptic encephalopathy, intellectual disability, aphasia and autism." (PMID 37284462, 2023).
West Syndrome (7 papers, 2012 to 2024). "Similar mutations in SPTAN1 that encodes alpha II spectrin cause severe and usually lethal neurodevelopmental defects including one form of early infantile epileptic encephalopathy type 5 (West syndrome)." (PMID 34528024, 2021). "Human mutations in αII spectrin (SPTAN1) link to early infantile epileptic encephalopathy (EIEE) type 5 (West Syndrome), characterized by refractory seizures, intellectual disability, agenesis of the corpus callosum and hypomyelination." (PMID 34528024, 2021). "There is evidence also that de novo in-frame mutations in SPTAN1 encoding α-II spectrin have dominant negative effects, causing a form of West Syndrome (infantile epilepsy with developmental delay)." (PMID 23236289, 2012).
Ataxia (6 papers, 2021 to 2023). Ataxia refers to impaired coordination of voluntary muscle movement. "Additional 3 probands with SPTAN1 variants presenting with seizures, ID, and ataxia/spasticity were identified." (PMID 36331550, 2023). "Although patient 7 was recruited under early-onset dystonia phenotype, she presented with abnormal eye movements, ataxia, myoclonus, and dyspraxia and had SPTAN1 variant, p.(Arg2124Cys)." (PMID 36331550, 2023). "Other phenotypes related to SPTAN1 mutations include cerebellar ataxias, hereditary-motor and sensory-motor neuropathies, and spastic paraplegia." (PMID 36831804, 2023). "It is worth noting that although SPTAN1 variants affecting intrahelical stabilizing interactions within spectrin repeats share a similar proposed pathogenic mechanism, they present a complex spectrum of spastic and ataxia phenotypes." (PMID 36831804, 2023). "Patient 10, who had pure ataxia, harbored a heterozygous splice alteration in SPTAN1 (NC_000009.12[SPTAN1_v001]:c.3519+2T>G)." (PMID 36331550, 2023). "SPTAN1 is a potential gene for ataxia and spastic paraplegia, and also the disruption of spectrin helices' interlinking might be a crucial aspect of the pathomechanism for the mutations." (PMID 35677823, 2022).
colon carcinoma (6 papers, 2014 to 2024). "Higher protein and mRNA levels of Sptan1 are associated with longer patient survival times in colon cancers." (PMID 39165691, 2024). "In a complementary in vitro model, SPTAN1 knockdown strains of three widely used colon cancer cell lines were less responsive to FOLFOX chemotherapy compared with SPTAN1-proficient control strains." (PMID 34298848, 2021). "Complementary in vitro experiments confirm that SPTAN1 knockdown strains of the colon cancer cell lines HT-29, HCT116 mlh1-2 and Caco-2 are less responsive to FOLFOX chemotherapy compared with SPTAN1-proficient control strains." (PMID 34298848, 2021). "Similar results were obtained for SPTAN1 knockdown strains of the colon cancer cell lines HCT116 mlh1-2 and Caco-2 (Figure A1 and Figure A2 in Appendix A)." (PMID 34298848, 2021). "To corroborate these findings in a different system, we then determined response to FOLFOX chemotherapy in human HT-29 colon cancer cells with stable knockdown of SPTAN1 expression." (PMID 34298848, 2021). "The low expression of SPTAN1 reduced the ability of cell-to-cell contact, which facilitated the metastasis of colon cancer cells." (PMID 33552118, 2020). "Nine cancer cell lines as well as fresh and paraffin embedded colon cancer tissue from 12 patients were used in gene expression studies of SPTAN1 and MLH1." (PMID 24456667, 2014). "On the other hand, and perhaps in a different cellular context, SPTAN1 may promote tumour cell motility and invasiveness, consistent with the protein’s known role in colon cancer cell migration." (PMID 34298848, 2021). "Finally, we generate SPTAN1 knockdown strains of three widely used colon cancer cell lines, to further probe the impact of differential SPTAN1 expression levels on treatment responses to FOLFOX chemotherapy." (PMID 34298848, 2021). "Our findings are consistent with the loss of SPTAN1 expression seen in MLH1-deficient colon cancers that are notoriously unresponsive to standard chemotherapies in the adjuvant setting." (PMID 34298848, 2021).
lung carcinoma (6 papers, 2017 to 2022). "Completely different from the traditional function of DNA ICLs caused by MMC, the miR-128-3p-SPTAN1 axis is a novel molecular mechanism for inhibiting the repair of DNA ICLs and could serve as an excellent potential auxiliary to treat lung cancer." (PMID 28938540, 2017). "Our findings are in line with a recent report suggesting that higher SPTAN1 gene expression levels are associated with better survival outcomes in patients with lung cancer, and may prompt similar investigations into the prognostic role of actin-binding proteins in other cancers." (PMID 34298848, 2021). "Until now, downregulation of SPTAN1 was described only in lung cancer, in a lung metastasis of prostate cancer, and in MMR-deficient CRC." (PMID 31186638, 2019). "Twenty years later, SPTAN1 again became a gene of interest in lung cancer when it was identified by exome and mRNA sequencing in lung adenocarcinoma." (PMID 31186638, 2019). "Here, we report that miR-128-3p can attenuate repair of DNA ICLs by targeting SPTAN1 (αII Sp), resulting in cell cycle arrest and promoting chromosomal aberrations in lung cancer cells treated with MMC." (PMID 28938540, 2017). "In this study, we describe a novel function for miR-128-3p, whereby regulation of chromosomal stability and cell cycle progression occur through SPTAN1 in lung cancer cells treated with MMC." (PMID 28938540, 2017). "MMC treatment not only cross-links DNA but also inhibits expression of SPTAN1 through miR-128-3p to disrupt recruitment of DNA repair-associated proteins (FANCA and XPF), with dual destructive effects in lung cancer cells." (PMID 28938540, 2017). "miR-128-3p induced cell cycle arrest and genomic instability in mitomycin C-treated lung cancer cells through inhibition of SPTAN1, and these findings may be used in adjuvant lung cancer therapy." (PMID 36793341, 2022). "Suppression of SPTAN1 expression could be executed by microRNA-128-3p as shown in lung cancer cells." (PMID 31186638, 2019). "Interestingly, in vitro data of lung cancer cells demonstrated that SPTAN1 is suppressed by microRNA-128-3p, which led to enhanced sensitivity to cytostatic mitomycin C (MMC) by limiting DNA repair capacity." (PMID 31186638, 2019). "In summary, the results demonstrate that miR-128-3p accelerates cell cycle arrest and chromosomal instability in MMC-treated lung cancer cells by suppressing SPTAN1, and these findings could be applied for adjuvant chemotherapy of lung cancer." (PMID 28938540, 2017). "SPTAN1 suppression by microRNA-128-3p led to enhanced sensitivity to cytostatic MMC by limiting DNA repair in lung cancer cells which could be applied for adjuvant chemotherapy in lung cancer." (PMID 31186638, 2019). "The miR-128-3p-SPTAN1 axis provides a novel avenue for understanding the mechanism of chemosensitivity, and miR-128-3p could be a candidate molecular target for improving the efficacy of lung cancer chemotherapy." (PMID 28938540, 2017). "Here, we demonstrate that overexpression of miR-128-3p down-regulates SPTAN1 expression via translational repression and results in the failure to recruit FANCA and XPF to facilitate chromosomal instability after MMC-induced DNA ICL damage in lung cancer cells." (PMID 28938540, 2017).
developmental delay (5 papers, 2012 to 2025). "Also, improved bioinformatics by new copy number variants (CNVs) caller has allowed the detection of a heterozygous multi-exon deletion in individual U075 (in-frame deletion of SPTAN1 exons 10–12), who presented with developmental delay and hypotonia." (PMID 32963807, 2020).
Epileptic encephalopathy (5 papers, 2014 to 2023). A condition in which epileptiform abnormalities are believed to contribute to the progressive disturbance in cerebral function. "There are two genes on the fringe of both clusters, PNKP and SPTAN1, showing weak co-expression with the majority of Epileptic Encephalopathy genes." (PMID 25014031, 2014). "SPTAN1 encodes non-erythrocyte αII spectrin, and several patients with epileptic encephalopathies have been reported with SPTAN1 mutations." (PMID 35327449, 2022).
ovarian carcinoma (4 papers, 2007 to 2023). A malignant neoplasm originating from the surface ovarian epithelium. "In ovarian cancer cells, inhibition of SPTAN1 cleavage and apoptosis has been described via an alternatively spliced caspase 2 short isoform (casp-2s)." (PMID 31186638, 2019). "Here, SPTAN1 levels were increased in post-CT ovarian cancer and SPTAN1 was classified as a tumorigenic gene." (PMID 31186638, 2019). "ABCA3 was previously identified as an ER-regulated gene, which supports its involvement in breast tumorigenesis, and SPTAN1 was involved in chemotherapy resistance in ovarian cancer, which makes this gene a potential target for cancer treatment." (PMID 17280605, 2007). "In this regard, in ovarian cancer, SPTAN1 expression increased after successful chemotherapy." (PMID 38069214, 2023).
developmental and epileptic encephalopathy (3 papers, 2022 to 2026). An epilepsy associated with developmental impairment that may be due to either the underlying etiology or the superimposed epileptic activity, or both. "Mendelian disease-gene links are increasingly being recognized for the spectrin genes, with SPTAN1, SPTBN1, SPTBN2 and SPTBN4 linked to neurological diseases such as developmental and epileptic encephalopathy (DEE), ataxia, hereditary spastic paraplegia, and hereditary motor neuropathy." (PMID 36238261, 2022).
developmental and epileptic encephalopathy, 5 (3 papers, 2019 to 2024). Any early infantile epileptic encephalopathy in which the cause of the disease is a mutation in the SPTAN1 gene. "Heterozygous mutations in SPTAN1 lead to early infantile epileptic encephalopathy-5 (EIEE5, OMIM# 613477), which is characterized by seizures with hypsarrhythmia, intellectual disability and delayed development." (PMID 31191255, 2019).
encephalopathies (3 papers, 2018 to 2023). "Modeling human SPTAN1 encephalopathies in laboratory animals has been challenging partially because no haploinsufficiency-related phenotypes unfold in heterozygous Spna2 deficient mice nor stable transgenic lines of mice mimicking missense human SPTAN1 mutations have been created to date." (PMID 36831804, 2023). "Further studies are needed for a better understanding of the phenotype/genotype correlation in SPTAN1-related encephalopathies." (PMID 29986434, 2018).
hereditary spastic paraplegia (3 papers, 2022 to 2025). Hereditary spastic paraplegias (HSP) comprise a genetically and clinically heterogeneous group of neurodegenerative disorders characterized by progressive spasticity and hyperreflexia of the lower limbs. "Statistically significant enrichment of rare (minor allele frequency < 1 × 10–5) probably damaging SPTAN1 variants was identified in families with hereditary ataxia (HA) or hereditary spastic paraplegia (HSP) (12/1142 cases vs 52/23,847 controls, p = 2.8 × 10–5)." (PMID 36331550, 2023). "Other SPTAN1 neurological disorders include juvenile-onset hereditary motor neuropathy and hereditary spastic paraplegia." (PMID 36551785, 2022).
metastatic tumors (3 papers, 2019 to 2021). "In addition, SPTAN1 levels were lower in metastatic compared with non-metastatic tumors." (PMID 30856214, 2019). "In a cohort of 189 patients with CRC, we recently showed that expression of the cytoskeletal scaffolding protein non-erythroid spectrin αII (SPTAN1) was lower in advanced metastatic tumours." (PMID 34298848, 2021).